LHCGR (luteinizing hormone/choriogonadotropin receptor)
Description:
Receptor for lutropin-choriogonadotropic hormone. The activity of this receptor is mediated by G proteins which activate adenylate cyclase.
Synonyms: LH/CG-R; LHR; LSH-R; LCGR; LGR2; LHRHR; ULG5; HHG; LH/CGR
Tractability: Small molecule: a structure with a bound ligand is known; it belongs to a druggable protein family. Antibody: UniProt places it where antibodies can reach, with high confidence; its Gene Ontology location is reachable by antibodies, with high confidence; UniProt predicts a signal peptide or a membrane-spanning region; the Human Protein Atlas places it where antibodies can reach. PROTAC: a small molecule that binds it is known. Other modalities: an approved drug acts on it.
Target class: Membrane receptor; Family A G protein-coupled receptor; Peptide receptor (family A GPCR); Glycohormone receptor
Chemical probes: BAY-298 (high quality), BAY-899 (high quality)
Gene: Protein-coding gene on chromosome 2 (48,686,774 to 48,755,730, reverse strand). Ensembl gene ENSG00000138039.
Subcellular location: Cell membrane
Subcellular location (Human Protein Atlas): Plasma membrane; Centriolar satellite
Pathways (Reactome):
Signal Transduction: G alpha (s) signalling events; Hormone ligand-binding receptors
Gene Ontology:
Molecular function: luteinizing hormone receptor activity; choriogonadotropin hormone binding; choriogonadotropin hormone receptor activity; G protein-coupled peptide receptor activity; G protein-coupled receptor activity; protein-hormone receptor activity
Biological process: cellular response to luteinizing hormone stimulus; cognition; luteinizing hormone signaling pathway; adenylate cyclase-activating G protein-coupled receptor signaling pathway; cellular response to gonadotropin stimulus; G protein-coupled receptor signaling pathway; G protein-coupled receptor signaling pathway, coupled to cyclic nucleotide second messenger; hormone-mediated signaling pathway; male genitalia development; male gonad development; ovarian follicle development; ovulation cycle process; phospholipase C-activating G protein-coupled receptor signaling pathway; positive regulation of inositol trisphosphate biosynthetic process; cellular response to hormone stimulus; response to gonadotropin
Cellular component: plasma membrane; endosome; membrane
Genetic constraint (gnomAD): Loss-of-function variants: 38 observed, 47.15 expected, observed/expected ratio (o/e) 0.81, 90% interval 0.62 to 1.06. The upper end of that interval is the gene's LOEUF score, 1.06, which puts it in group 4 of 6, group 1 being the genes least tolerant of losing a copy. Missense variants: 779 observed, 777.05 expected, observed/expected ratio (o/e) 1, 90% interval 0.94 to 1.06. Synonymous variants: 308 observed, 297.74 expected, observed/expected ratio (o/e) 1.03, 90% interval 0.94 to 1.14.
Homologues: Orthologues: chimpanzee LHCGR (99% identical), macaque LHCGR (97% identical), rabbit LHCGR (89% identical), pig LHCGR (87% identical), dog LHCGR (87% identical), guinea pig LHCGR (84% identical), mouse Lhcgr (82% identical), rat Lhcgr (81% identical), tropical clawed frog lhcgr (65% identical), zebrafish lhcgr (51% identical), Drosophila melanogaster Lgr1 (38% identical), Caenorhabditis elegans fshr-1 (29% identical). Paralogues in human: FSHR (52% identical), TSHR (51% identical).
Diseases named in the same sentence as LHCGR in open-access papers:
LHCGR is named in the same sentence as 99 diseases in open-access papers, as found by Europe PMC text mining. Sharing a sentence is not in itself a finding about the gene and the disease. The quoted sentences say what the papers report.
Infertility (19 papers, 2016 to 2025). "Some studies have determined that inactivating alterations in LHCGR gene are associated with increased LH level, enlarged ovaries, oligomenorrhea, resistance to LH or hCG hormones, and infertility." (PMID 38649916, 2024). "We also report one VUS associated with the LHCGR gene, which has been reported to be related to Leydig cell hypoplasia with hypergonadotropic hypogonadism leading to infertility." (PMID 39830005, 2024). "It has been revealed that two common SNPs (rs4539842 and rs2293275) in the LHCGR gene are associated with the outcome of IVF in Iranian infertile women." (PMID 31897388, 2019). "In humans inactivating mutations in the LHCGR gene have been shown to cause infertility in both male and female." (PMID 27716033, 2016). "In females, most LHCGR variants exhibit minimal effects on reproductive function; however, some inactivating polymorphisms are linked to conditions such as oligo-/amenorrhea, infertility, empty follicle syndrome, and higher risks of developing polycystic ovarian syndrome." (PMID 40723290, 2025). "Sources revealed 235 different genes linked to ovulatory dysfunction and infertility including follicle-stimulating hormone receptor (FSHR), luteinizing hormone/choriogonadotropin receptor (LHCGR), and bone morphogenic protein 15 (BMP15)." (PMID 40535332, 2025). "We found variants in genes categorized into isolated infertility (AR and CFTR), reproductive disorders (SRD5A2), and endocrine disorders (LHCGR and CYP21A2)." (PMID 39830005, 2024). "This prospective cohort study was conducted to determine the genotypic distribution of LHCGR N312S SNP in infertile Indian women undergoing ART and to evaluate the impact of this polymorphism on ART outcomes." (PMID 38022167, 2023). "Dysfunction of LHCGR in GCs can lead to ovarian insufficiency, impaired ovulation, infertility, and, in some cases, ovarian tumors." (PMID 37628741, 2023). "Hemorrhagic ovaries, anovulation and infertility observed in tKrasMT females are similar to that of female mice (KiLHRD582G) expressing the constitutively active mutant LHCGR." (PMID 36060690, 2022). "The used LHCGR ELISA showed that young healthy men had the highest concentration of serum LHCGR, whereas infertile men or patients with benign tumors had lower serum LHCGR levels." (PMID 32466562, 2020). "It has been shown that targeted disruption of the LHCGR gene in embryonic stem cells results in infertility in both sexes." (PMID 31897388, 2019). "Inactivating mutations in a number of these GPCRs have been shown to result in intracellular retention and infertility, including the LH receptor (LHCGR/LHR), FSH receptor (FSHR), and GnRHR, with all three being amenable to pharmacological chaperone rescue and restoration of signalling." (PMID 35562976, 2022). "Cross-sectional, longitudinal, and intervention studies on 195 healthy boys and men and 396 men with infertility, anorchia, or Klinefelter Syndrome (KS) were used to correlate LHCGR measured in serum, seminal fluid, urine, and hepatic/renal artery and vein with gonadal function." (PMID 33809538, 2021). "Therefore, the objective of the current study was to investigate the prevalence of exons 1(rs4539842) and 10(rs12470652, rs2293275) polymorphisms of the LHCGR gene and its relationship with successful IVF in Iranian infertile women." (PMID 31897388, 2019). "Therefore, identifying other variants in the TMDs of LHCGR, specifically the third, could provide valuable insights into the molecular mechanisms underlying LCH, infertility, and other related conditions." (PMID 38526829, 2024). "Thus, dysfunction of the LHCGR in females can lead to infertility." (PMID 35408615, 2022). "Studies with a large sample size of Indian infertile women undergoing ART with GnRH antagonist protocol are required to confirm the findings of our study and to assess the impact of LHCGR N312S SNP on ART outcomes." (PMID 38022167, 2023).
Infertility (continued). "The aim of our study was to investigate the genotypic distribution of the LHCGR N312S SNP and how it affects clinical and reproductive outcomes in women undergoing ART in the infertile Indian population." (PMID 38022167, 2023). "There are few data on the LHCGR gene's N312S SNP and its effect on ART outcomes, especially in the Indian infertile population, and the results are contradictory." (PMID 38022167, 2023). "Hence, assessing LHCGR N312S SNP may help us to predict reproductive outcomes in ART and aid in better counseling for infertile couples." (PMID 38022167, 2023).
polycystic ovary syndrome (19 papers, 2012 to 2026). A disorder that manifests as multiple cysts on the ovaries. "LHCGR polymorphisms are associated with polycystic ovary syndrome in women with a high body mass index (BMI) and waist-to-hip ratio." (PMID 40427364, 2025). "This study was conducted to analyze the association of Luteinizing Hormone/Choriogonadotropin Receptor (LHCGR) gene rs4953616 and rs7371084 polymorphisms with the risk of polycystic ovary syndrome (PCOS) in Punjab, India." (PMID 38129424, 2023). "This is the first study from Punjab carried out to investigate the possible association of exon 10 variants of LHCGR gene for the development of polycystic ovary syndrome." (PMID 36585675, 2022). "Regarding the LHCGR gene polymorphisms and their associations with other diseases, different studies have shown that rs2293275 is associated with polycystic ovarian syndrome." (PMID 31897388, 2019). "In addition, LHCGR resides near a potential susceptibility locus for polycystic ovary syndrome (PCOS), which is characterized by anovulation/oligo-ovulation and elevated androgen levels." (PMID 23883350, 2013). "LHCGR (2p16.3) encodes the luteinizing hormone receptor which was associated with polycystic ovary syndrome (PCOS) in a recent GWAS." (PMID 22829776, 2012). "Several researchers have discovered a relationship between N312S and polycystic ovarian syndrome (PCOS), with the N variant making LHCGR more sensitive." (PMID 38022167, 2023). "For example, hypomethylation of the promoter region and subsequent activation of the LHCGR gene is a potential mechanism underlying the susceptibility of polycystic ovary syndrome (PCOS), which is the most common endocrine disorder in reproductive-aged women and characterized by hyperandrogenism." (PMID 34697294, 2021). "It has been demonstrated that the downregulation of miR-592 is associated with a high level of luteinizing hormone/chorionic gonadotropin receptor (LHCGR), an important factor for hyperandrogenemia in PCOS." (PMID 33477832, 2021). "Presumably, crosstalk disturbances may lead to the overexpression of LHCGR and thus to the development of polycystic ovary syndrome." (PMID 30619090, 2018). "In addition, polycystic ovaries display increased LHCGR expression, which may render them hypersensitive to LH effects (which may also be upregulated), including ERK1/2- and AKT-mediated survival signals." (PMID 38509545, 2024). "Recently, a functional network, including miR-130b-3p, DENND1A.V.2, LHCGR, RSB5B, and the signaling pathways they target, was proposed to potentially mediate PCOS-related hyperandrogenemia." (PMID 33746952, 2021). "In addition, increased expression of LHCGR and CYP17A1 in human polycystic ovaries’ theca cells has been observed." (PMID 30944702, 2019).
ovarian carcinoma (10 papers, 2011 to 2024). A malignant neoplasm originating from the surface ovarian epithelium. "High FSHR or high LHCGR expression in patients with all subtypes of high-grade ovarian cancer was significantly associated with longer progression-free survival (PFS) and overall survival (OS)." (PMID 33374698, 2020). "We showed that higher FSHR and LHCGR expression are associated with early stage, low grade ovarian cancer and that FSHR and LHCGR expression is reduced in HGSOC compared to benign ovarian tumors." (PMID 33374698, 2020). "This study highlights that lower FSHR and LHCGR expression is associated with a more aggressive epithelial ovarian cancer phenotype and promotes pro-metastatic behaviour." (PMID 33374698, 2020). "We have shown that: (i) high FSHR or LHCGR mRNA expression is associated with early-stage and low-grade ovarian cancer." (PMID 33374698, 2020). "Further evidence from three former studies suggests that GnRs exert opposing roles in ovarian cancer with LHCGR being linked to favorable prognosis and FSHR being associated to shorter overall survival." (PMID 23951246, 2013). "Together, our findings support the hypothesis that reduced FSHR and/or LHCGR is associated with a poorer prognosis and can promote pro-metastatic ovarian cancer cell behaviour." (PMID 33374698, 2020). "This study investigated whether FSHR and LHCGR mRNA and protein levels are associated with ovarian cancer progression and if the knockdown of these gonadotrophin receptors affects invasive behavior of serous ovarian cancer cells in vitro." (PMID 33374698, 2020). "FSHR and LHCGR mRNA and protein expression were assessed in a range of human ovarian cancer cell lines by qRT-PCR and western blotting, respectively." (PMID 33374698, 2020). "Using the publicly available CSIOVDB database, FSHR and LHCGR expression was increased in early-stage ovarian cancer (stage I) compared to stage II, III or IV cancers (p < 0.01)." (PMID 33374698, 2020). "Reflecting the role of β-arrestins as scaffold proteins linked to the GPCRs activity, correlations between the β-arrestin 2 and FSHR and LHCGR expression was identified ovarian cancer tissue." (PMID 33042017, 2020). "LHCGR overexpression was associated with reduced proliferation, migration and invasion in SKOV3 ovarian cancer cells supporting our findings that LHCGR knockdown promotes invasion." (PMID 33374698, 2020). "Our findings agree with previous studies that have reported significantly decreased LHCGR expression in malignant ovarian tumors compared to benign tumors and a steady decrease in LHCGR expression from low-grade to high-grade ovarian cancer." (PMID 33374698, 2020). "The neutralizing effect of LH/FSH signalling on GPER-mediated impact on survival was supported by our tissue culture data: ovarian cancer cell proliferation was profoundly reduced when GPER was activated in case of inactivated LH/LHCGR or FSH/FSHR pathways." (PMID 23951246, 2013). "Follicle stimulating hormone receptor (FSHR) and luteinizing hormone receptor (LHCGR) were demonstrated to impact upon survival of patients suffering from epithelial ovarian cancer (EOC)." (PMID 23951246, 2013). "We performed in vitro stimulation assay in two out of three GPER positive ovarian cancer cell lines expressing either FSHR or LHCGR." (PMID 23951246, 2013). "In addition to hCG, LHCGR expression was also an independent prognostic factor for the occurrence, progression, and overall survival of patients with ovarian cancer." (PMID 34941061, 2021). "The ‘gonadotropin theory’ proposes that chronically elevated FSH and LH levels may lead to increased activation of FSHR and LHCGR, respectively, and subsequently stimulate ovarian cancer proliferation." (PMID 33374698, 2020). "Similarly, FSHR and LHCGR expression was increased in low-grade ovarian cancers (grade I), compared to high grade ovarian cancers (grade II or grade III, p < 0.01)." (PMID 33374698, 2020).
ovarian carcinoma (continued). "This hormone was shown to be associated with an increased 5-years survival in LHCGR positive/FSHR negative ovarian cancer cases." (PMID 33042017, 2020). "However, few studies have explored the expression of FSH and LH receptors (FSHR and LHCGR) in ovarian cancer, and their functional roles in cancer progression remain inconclusive." (PMID 33374698, 2020). "In addition, hCG expression was positively correlated with LHCGR expression in ovarian cancer tissues because hCG could also bind to the LH receptor." (PMID 34941061, 2021). "Several GPCRs are overexpressed in ovarian cancer including the lysophosphatidic acid receptor (LPAR), C-X-C chemokine receptor type 4 (CXCR4), follicle-stimulating hormone receptor (FSHR) and luteinizing hormone/choriogonadotropin receptor (LHCGR)." (PMID 40836974, 2024). "Using Kaplan–Meier online plotter, we also observed a significant relationship between high LHCGR expression and increased PFS and OS in all ovarian cancers and patients with high grade disease." (PMID 33374698, 2020). "A mass spectrometry approach would be useful to confirm and distinguish the different LHCGR and FSHR bands observed in the ovarian cancer cell lines and ovarian tissues." (PMID 33374698, 2020). "We investigated the functional role of gonadotropin receptors in ovarian cancer by knocking down FSHR and LHCGR in OVCAR3 and COV362 cell lines and assessing their effects on cell invasion in vitro." (PMID 33374698, 2020). "In a recent study we found an opposed prognostic value of LHCGR and FSHR in ovarian cancer in almost the same panel of patients as described within this study." (PMID 23036050, 2012). "This agrees with a study in 1997 examining mRNA expression of LHCGR in early and advanced stage ovarian cancer (n = 43) demonstrating that negative LHCGR expression was associated with reduced OS (p = 0.047)." (PMID 33374698, 2020). "It is feasible that LH and FSH may promote ovarian cancer proliferation in the presence of FSHR and LHCGR however, tumor cells lacking LHCGR or FSHR no longer depend on gonadotropins for their growth and exhibit more aggressive behaviour." (PMID 33374698, 2020). "Ovarian cancer cell lines were used to study how FSH and LH regulate GPER and whether GPER activation differentially affects in vitro cell proliferation in presence/absence of activated FSHR/LHCGR." (PMID 23951246, 2013).
breast cancer (7 papers, 2013 to 2025). A primary or metastatic malignant neoplasm involving the breast. "One of them, the LHCGR variant 18insLQ, is associated with the early onset of breast cancer and short disease-free survival." (PMID 28754015, 2017). "Another cause for the differing effect of HCG on breast cancer cells could be the fact that the LHCGR carries a large number of polymorphisms." (PMID 28754015, 2017). "Moreover, the LHCGR 312Asn allele can be regarded as a weak breast cancer risk allele." (PMID 31897388, 2019). "Interestingly, LHCGR 18insLQ has a high frequency among Northern-European Caucasians that are characterized by a higher prevalence of breast cancer compared to other ethnic groups, leading to the speculation that the LHCGR genotype may be linked to disease risk." (PMID 28754015, 2017). "We confirmed a high expression of Luteinizing hormone/choriogonadotropin receptor (LHCGR) in TGCA data set for breast cancer and in a panel of breast cancer cell lines, however LHCGR was found to be expressed irrespective of β-hCG expression status." (PMID 28869585, 2017).
empty follicle syndrome (6 papers, 2020 to 2025). "On BTA11, a mutation in the LHCGR (luteinizing hormone/choriogonadotropin receptor) gene was as the cause of empty follicle syndrome." (PMID 32171250, 2020). "(2023), patients with LHCGR mutations suffered empty follicle syndrome." (PMID 40535332, 2025). "Inherited mutations of LHCGR are shown to be related to oligo-ovulation or empty follicle syndrome." (PMID 36768772, 2023). "For example, mutations found in the LHCGR-encoding gene correlate with the empty follicle syndrome resulting in no oocytes retrieved during IVF." (PMID 37104276, 2023).